SOD1 (superoxide dismutase 1)
Diseases named in the same sentence as SOD1 in open-access papers (continued):
Sharing a sentence is not in itself a finding about the gene and the disease.
amyotrophic lateral sclerosis (continued). "Mutations in the protein superoxide dismutase-1 (SOD1) promote its misfolding and aggregation, ultimately causing familial forms of the debilitating neurodegenerative disease amyotrophic lateral sclerosis (ALS)." (PMID 38835240, 2024). "sod-1 encodes the ortholog of mammalian SOD1, which is a cytoplasmic SOD implicated in the development of amyotrophic lateral sclerosis and cancer." (PMID 39636673, 2024). "Drosophila melanogaster models have been pivotal in elucidating the role of the SOD1 gene in amyotrophic lateral sclerosis (ALS)." (PMID 39337454, 2024). "In April 2023, the antisense oligonucleotide tofersen was approved by the U.S. Food and Drug Administration (FDA) for treatment of SOD1-amyotrophic lateral sclerosis (ALS), after a decrease of neurofilament light chain (NfL) levels had been demonstrated." (PMID 38384337, 2024). "Among clinical trials, spinal ganglion toxicity was seen at autopsy in a patient with familial amyotrophic lateral sclerosis (ALS) and mutations in the gene encoding superoxide dismutase 1 (SOD1) after intrathecal infusion of 4.2 × 1014 vg AAVrh10 containing anti-SOD1 microRNA (AAV-miR-SOD1)." (PMID 39594663, 2024). "Superoxide dismutase 1 (SOD1) is crucial in the pathogenesis of amyotrophic lateral sclerosis (ALS)." (PMID 39337454, 2024). "They tested 11C-MPC-6827 in transgenic mice bearing tau pathology (rTg4510) and amyotrophic lateral sclerosis pathology (SOD1*G93A)." (PMID 37238166, 2023). "Mutations in the gene encoding the ubiquitously expressed free radical scavenging enzyme superoxide dismutase-1 (SOD1) are found in 2–6% of amyotrophic lateral sclerosis patients." (PMID 36385230, 2023). "Whereas SLC7A11 is not expressed in motor neurons, SLC7A11 expression is induced in activated microglia in amyotrophic lateral sclerosis (ALS) mice carrying mutant SOD1, the gene encoding cytosolic superoxide dismutase (SOD)." (PMID 37175751, 2023). "In line with this, BDNF-dependent axonal transport has been found to be defective in the mouse model of amyotrophic lateral sclerosis SOD1." (PMID 37445838, 2023). "In their study, IKK2/NF‐κB was overexpressed in astrocytes of the SOD1 (G39A) mice, an amyotrophic lateral sclerosis (ALS) animal model." (PMID 36453496, 2023). "In the C9orf72 group, 10 out of 66 rated patients (15.2%), were consistent with diagnosis of FTD in neuropsychological examination which was higher compared to sporadic amyotrophic lateral sclerosis (18/304 (5.9%); P = 0.02) and SOD1 (0/11 (0%), P = 0.34)." (PMID 37006326, 2023). "Beneficial impact of both overexpression or deletion of P2X4 described in SOD1 mouse model of amyotrophic lateral sclerosis suggests that P2X4 expressed in motoneurons, and microglia exert opposite effects in ALS pathogenesis." (PMID 38239187, 2023). "Another ASO, Tofersen, targets the superoxide dismutase 1 (SOD1) mRNA in SOD1-dependent amyotrophic lateral sclerosis (ALS)." (PMID 36986629, 2023). "IPA toxicity analysis of SOD1 identified superoxide radicals’ degradation as the leading signaling pathway followed by apelin adipocyte signaling, amyotrophic lateral sclerosis signaling, NRF2-mediated oxidative stress response, and sirtuin signaling pathways." (PMID 36672132, 2023). "The age of onset in C9orf72 was older compared to SOD1, but younger compared to sporadic amyotrophic lateral sclerosis." (PMID 37006326, 2023). "Identified as the first gene with mutations in Amyotrophic lateral sclerosis (ALS),SOD1 is a determinant for studying diseases of aging and neurodegeneration." (PMID 37860271, 2023). "For example, tofersen, a 2′-MOE ASO designed to target superoxide dismutase (SOD1) for amyotrophic lateral sclerosis (ALS), recently completed phase 3 clinical trial testing and received FDA approval in April 2023." (PMID 38192302, 2023). "Plant flavonols also protect against Aβ aggregation in AD or slow SOD1 (superoxide dismutase 1) aggregation in ALS (amyotrophic lateral sclerosis)." (PMID 37571391, 2023).
amyotrophic lateral sclerosis (continued). "Rilmenidine has been shown to induce autophagy in SOD1‐ or TDP43‐mutant mice models of amyotrophic lateral sclerosis." (PMID 36670049, 2023). "The GSE106382 study generated expression data of induced pluripotent stem cells (iPSCs) from healthy controls, sporadic amyotrophic lateral sclerosis (ALS) and familial ALS patients including a subgroup of familial cases who carried a pathogenic mutation in the SOD1 gene (SOD1 ALS)." (PMID 35609980, 2022). "Furthermore, the methodology was used for CRISPR-based editors to treat amyotrophic lateral sclerosis (ALS), which is due to mutations in the superoxide dismutase 1 (SOD1) gene in a G93A-SOD1 mouse model of ALS." (PMID 35211511, 2022). "In the mouse model of amyotrophic lateral sclerosis, a misfolded mutant of superoxide dismutase 1 (SOD1) directly inhibits VDAC1 conductance, disclosing the connection of VDAC1 and SOD1 in oxidative stress." (PMID 35449127, 2022). "The heterodimerization of WT Cu, Zn superoxide dismutase-1 (SOD1), and mutant SOD1 might be a critical step in the pathogenesis of SOD1-linked amyotrophic lateral sclerosis (ALS)." (PMID 36265587, 2022). "Base-editing tools have also been tested in the treatment of amyotrophic lateral sclerosis in SOD1(G93A) mice, which are characterized by an especially aggressive course of the neurodegenerative disease and have an average lifespan of ∼120 days." (PMID 36032737, 2022). "SOD1 has previously been reported to correlate with neurodegenerative diseases, such as amyotrophic lateral sclerosis and AD." (PMID 36466169, 2022). "We also reported a Rubicon neuronal profile in the spinal cord of the amyotrophic lateral sclerosis (ALS) SOD1-mutant mice model." (PMID 35740989, 2022). "Mutations in SOD1 can cause conformational instability or misfolding of the SOD1 protein, and comprise the second major genetic risk factor associated with amyotrophic lateral sclerosis (ALS), accounting for 20% of familial ALS (fALS) cases." (PMID 36499600, 2022). "All three UPR pathways are downregulated upon CDNF treatment in SOD1 mice modeling amyotrophic lateral sclerosis (ALS)." (PMID 35129674, 2022). "Recent data from the Phase 1/2 clinical trials of Tofersen, a gapmer designed to suppress SOD1 as a treatment for amyotrophic lateral sclerosis (ALS), reported pleocytosis within the CSF in 42% of the trial participants." (PMID 35464859, 2022). "Mutations in SOD1 cause familial amyotrophic lateral sclerosis (ALS)." (PMID 36523604, 2022). "Eukaryotic Cu, Zn-superoxide dismutase (SOD1) is primarily responsible for cytotoxic filament formation in amyotrophic lateral sclerosis (ALS) neurons." (PMID 36224351, 2022). "Cx30 is upregulated on activated astroglia in central nervous system inflammatory lesions, including spinal cord lesions in mutant superoxide dismutase 1 (mSOD1) transgenic amyotrophic lateral sclerosis (ALS) model mice." (PMID 36555685, 2022). "As an example, mutations in superoxide dismutase (Cu-Zn), also known as superoxide dismutase 1 (SOD1), cause motor neuron degeneration in amyotrophic lateral sclerosis patients, of which 60% develop pain." (PMID 36324872, 2022). "Another study identified ERp57/PDIA3 as protective against mutant SOD1-induced cellular pathology in amyotrophic lateral sclerosis." (PMID 35109791, 2022). "Characterization of the structure of an overoxidation-mimicking double mutant of superoxide dismutase SOD1 shows the production of more cytotoxic filaments seen in amyotrophic lateral sclerosis (ALS) neurons." (PMID 36224351, 2022). "Demethylation of the D-loop region and elevated mtDNAcn have been observed in both sporadic amyotrophic lateral sclerosis (ALS) patients and carriers of ALS-linked SOD1 mutations, which suggests that D-loop methylation may negatively regulate mtDNAcn." (PMID 34983647, 2022).
amyotrophic lateral sclerosis (continued). "Amyloid aggregation of copper, zinc superoxide dismutase SOD1, an essential component of the cellular antioxidant defense system, is associated with amyotrophic lateral sclerosis (ALS), a neurological disease causing the death of motor neurons and muscular paralysis." (PMID 34205510, 2021). "In addition, SOD1 is a gene associated with amyotrophic lateral sclerosis (ALS), which has been associated with GW service and is also postulated to be involved in gene-by-environment interactions." (PMID 34942860, 2021). "Mutations in the SOD1 gene has also long been associated with amyotrophic lateral sclerosis (ALS)." (PMID 34746916, 2021). "Intriguingly, similar increases were shown in patients with amyotrophic lateral sclerosis and Down syndrome who carry an extra copy of the SOD1 gene." (PMID 34948180, 2021). "In Amyotrophic Lateral Sclerosis (ALS), the misfolded Cu/Zn-superoxide dismutase (SOD1) protein was the first protein disfunction associated with familiar ALS." (PMID 34830171, 2021). "Aggregation and accumulation of the fibrillar inclusions of SOD1, consisting of two β-barrels in the native state, occur during the development of sporadic and hereditary forms of human amyotrophic lateral sclerosis (ALS)." (PMID 34768745, 2021). "Resveratrol, a SIRT1 activator, reportedly protects the amyotrophic lateral sclerosis (ALS) cell model from mutant superoxide dismutase 1 (SOD1)-mediated toxicity by up-regulation of SIRT1 expression." (PMID 33737560, 2021). "Amyotrophic lateral sclerosis (ALS) is a rare motor neuron disease, strongly associated with mutations in SOD1, a ROS scavenging enzyme." (PMID 34064758, 2021). "Mutations in SOD1 have been shown to cause Amyotrophic Lateral Sclerosis (ALS)." (PMID 33504070, 2021). "Moreover, there is a tight connection between SOD1 (superoxide dismutase; in which toxic gain-of-function mutations lead to aggregation in amyotrophic lateral sclerosis [ALS]) and autophagy dysfunction." (PMID 34309456, 2021). "This is particularly the case for amyotrophic lateral sclerosis (ALS), a multigenic disease resulting from mutations in various genes including superoxide dismutase (SOD1), TDP43 or FUS protein." (PMID 32961072, 2020). "It has been reported in a recent study that HA counteracts proinflammatory microglia phenotype in the SOD1-G93A mouse model of Amyotrophic Lateral Sclerosis." (PMID 32872194, 2020). "Some evidence suggests that intermolecular disulfide bonds in mutant superoxide dismutase 1 (SOD1) may have a role in its aggregation, a hallmark of some familial amyotrophic lateral sclerosis (ALS) variants." (PMID 32582695, 2020). "Only one in vivo study assessed CBN (5 mg·kg−1 per day) in an SOD1 model of amyotrophic lateral sclerosis." (PMID 32608035, 2020). "Mutation in the SOD1 gene results in the production of dysfunctional SOD1 that accumulates as toxic protein in the cells and results in familial amyotrophic lateral sclerosis (ALS)." (PMID 32604776, 2020). "Such fibril formation by superoxide dismutase I (SOD1) is considered to be related to amyotrophic lateral sclerosis, a late-onset and fatal disorder." (PMID 32864220, 2020). "Similar to this study, an unmethylated profile for various SOD1 promoter region CpG sites occurs in the cerebral cortex and blood cells in lateral amyotrophic sclerosis patients, as well as in the control individuals." (PMID 32267380, 2020). "Important clues are provided by the systemic effects on energy metabolism observed in mutant SOD1-mediated amyotrophic lateral sclerosis (ALS)." (PMID 32927603, 2020). "In NDs, EVs were initially characterized as vehicles for misfolded or dysfunctional mutant proteins, such as amyloid-beta oligomers in Alzheimer’s disease (AD), SOD1 in amyotrophic lateral sclerosis (ALS), or α-Syn in PD." (PMID 32948090, 2020).
amyotrophic lateral sclerosis (continued). "Finally, amyotrophic lateral sclerosis (ALS)-linked gene, including SOD1, and genes causing FTD, including GRN, are also robustly expressed in GNs at all assayed time points." (PMID 33281596, 2020). "Similarly, aggregated/misfolded mutated Cu/Zn superoxide dismutase (SOD1) associate with amyotrophic lateral sclerosis (ALS)." (PMID 32526949, 2020). "Amyotrophic lateral sclerosis (ALS) is a progressive and fatal neurodegenerative disease associated with aggregation of superoxide dismutase 1 (SOD1) protein." (PMID 32742795, 2020). "Finally, we demonstrated the increased expression of S100A4 also in fibroblasts derived from amyotrophic lateral sclerosis (ALS) patients carrying SOD1 pathogenic variants." (PMID 31623154, 2019). "Another example from the same near-ordered complex type is the superoxide dismutase SOD1, which is able to form aggregates in amyotrophic lateral sclerosis." (PMID 31683980, 2019). "In this investigation, CLR01 inhibited abnormal SOD1 self-assembly in vitro, as well as in vivo, as being shown on the G93A-SOD1 mouse model of amyotrophic lateral sclerosis (ALS)." (PMID 31632951, 2019). "SOD1 has been connected to the development of amyotrophic lateral sclerosis (ALS), cancer, ischemia, and altered glucose metabolism." (PMID 29478325, 2019). "Not only did supplementary Pgk1 enhance NOM in defective cells, but injection of Pgk1 rescued denervation in muscle-specific NogoA-overexpression of zebrafish and an Amyotrophic Lateral Sclerosis mouse model, SOD1 G93A." (PMID 31361595, 2019). "We tested this hypothesis in a cell culture model of familial amyotrophic lateral sclerosis (ALS) with Cu/Zn superoxide dismutase (SOD1) mutation." (PMID 31658977, 2019). "Amyotrophic lateral sclerosis (ALS) is a neurodegenerative disease characterized by loss of motor neurons, and mutations in more than 30 genes, including superoxide dismutase 1 (SOD1), have been identified in the disease." (PMID 31617312, 2019). "Despite the genetic heterogeneity reported in familial amyotrophic lateral sclerosis (ALS) (fALS), Cu/Zn superoxide-dismutase (SOD1) gene mutations are the second most common cause of the disease, accounting for around 20% of all families (ALS1) and isolated sporadic cases (sALS)." (PMID 31781168, 2019). "One of the most common rodent models of amyotrophic lateral sclerosis are mice with hSOD1 mutation (Jackson Laboratory; B6SJL-Tg(SOD1*G93A)1Gur/J, also known as SOD1-G93A stock# 002726)." (PMID 30692571, 2019). "The impairment of SOD1 maturation has been also related to the onset of severe disease states, including amyotrophic lateral sclerosis (ALS)." (PMID 30654299, 2019). "SOD1 misfolding and aggregation is correlated with cytotoxicity in neurodegenerative diseases such as amyotrophic lateral sclerosis." (PMID 30654299, 2019). "Mutations in superoxide dismutase-1 (SOD1) cause amyotrophic lateral sclerosis (ALS)." (PMID 29703933, 2018). "The human Sod1 homolog has been identified as the first and major causative gene for autosomal dominant familial cases of amyotrophic lateral sclerosis (ALS), a fatal neurodegenerative disorder, and some sporadic ALS patients (~3%) also possess mutations in the SOD1 gene." (PMID 29951484, 2018). "Many neurodegenerative diseases, including Alzheimer's, Parkinson's, amyotrophic lateral sclerosis (ALS), are caused by the misfolding and aggregation of proteins such as tau, alpha‐synuclein, superoxide dismutase 1 (SOD1), and TAR DNA‐binding protein‐43 (TDP‐43; Lansbury & Lashuel, 2006)." (PMID 30143514, 2018). "Mutant SOD1 endoplasmic reticulum/Golgi transport of SOD1 in amyotrophic lateral sclerosis (ALS) has also been demonstrated." (PMID 29881358, 2018). "When Cu/Zn superoxide dismutase (SOD1), an anti-oxidative enzyme, undergoes misfolding, fibrillar aggregates are formed, which are a hallmark of a certain form of familial amyotrophic lateral sclerosis (ALS)." (PMID 30289953, 2018).
amyotrophic lateral sclerosis (continued). "Since KPT-330 was able to extend lifespan in nematodes, we sought to analyze its effect on the lifespan of a Sod1-based neurodegenerative model of amyotrophic lateral sclerosis (ALS) in flies (dsodH71Y)." (PMID 29768192, 2018). "In another research, an in vitro model of amyotrophic lateral sclerosis showed that cells transfected with the mutant SOD1 were more vulnerable to infectious stimuli of the bacteria than cells overexpressing normal SOD1." (PMID 28512644, 2017). "In contrast to human tissue and cultured cells, Nrf2 activity is consistently elevated in the spinal cord of SOD1-G93A rodent models of amyotrophic lateral sclerosis." (PMID 28820437, 2017). "In a mutant superoxide dismutase 1 (SOD1) model of amyotrophic lateral sclerosis, expression of the astrocytic α2 isoform was increased, and knockdown of the astrocyte α2 isoform protected motor neurons from degeneration." (PMID 28687727, 2017). "Amyotrophic lateral sclerosis (ALS) is characterized by the misfolding of Cu/Zn superoxide dismutase (SOD1) into aberrant conformations, which has been pinpointed as a central event in familiar and sporadic forms of the disease." (PMID 28197068, 2017). "Superoxide dismutase 1 (SOD1) is an important metalloprotein for cellular oxidative stress defence, that is mutated in familiar variants of Amyotrophic Lateral Sclerosis (fALS)." (PMID 29234142, 2017). "Parkin protects against misfolded SOD1 toxicity by promoting its aggresome formation and autophagic clearance in amyotrophic lateral sclerosis (ALS)." (PMID 27597885, 2016). "Moreover, this homodimeric metalloenzyme has been directly linked to both familial and sporadic amyotrophic lateral sclerosis (ALS), a devastating, late-onset motor neuronal disease, with more than 150 ALS-related mutations in the SOD1 gene." (PMID 27074676, 2016). "Approximately 20 % of familial Amyotrophic Lateral Sclerosis (ALS) is caused by mutations in superoxide dismutase (SOD1), which leads to misfolding of the SOD1 protein, resulting in a toxic gain of function." (PMID 27121871, 2016). "Another major human disorder that is linked to the Mia40 pathway is ALS (Amyotrophic lateral sclerosis), which is known to be associated with mutations of SOD1, that cannot form the disulfide bonds properly and become aggregated leading to impairment of the mitochondrial function." (PMID 27033519, 2016). "Conditions in which neuronal cells are not able to cope with MD and OS seem to lead or contribute to several neurodegenerative diseases including Amyotrophic Lateral Sclerosis (ALS), at least in the most studied superoxide dismutase 1 (SOD1)-linked genetic variant." (PMID 25741238, 2015). "In embryonic motoneurons from the mutant SOD1 mouse model of amyotrophic lateral sclerosis, CRMP4a is upregulated to promote axonal degeneration." (PMID 26064693, 2015). "The conserved region of mitochondrial LysRS interacts with mutant SOD1 in some cases of amyotrophic lateral sclerosis, or with the GagPol polyprotein of HIV-1 to package tRNA3Lys into viral particles." (PMID 25807264, 2015). "Granulocyte-colony stimulating factor (G-CSF) has been recently identified as a neurotrophic factor able to preserve motor functions, rescue motor units and extent survival in an animal model of amyotrophic lateral sclerosis, the SOD1 G93A mice." (PMID 26484174, 2015). "Transgenic mouse models expressing mutant superoxide dismutase 1 (SOD1) have been critical in furthering our understanding of amyotrophic lateral sclerosis (ALS)." (PMID 25468678, 2015). "In the SOD1(G93A) mouse model of amyotrophic lateral sclerosis (ALS), miR-133 as well as miR-206 are upregulated at symptomatic stages." (PMID 24664281, 2014). "Mutations in the copper/zinc superoxide dismutase (SOD1), TAR DNA-binding protein 43 (TDP-43), and FET family proteins are associated with the development of amyotrophic lateral sclerosis (ALS), a fatal neurodegenerative disease." (PMID 24804206, 2014).